CCL11 (C-C motif chemokine ligand 11)
Diseases named in the same sentence as CCL11 in open-access papers (continued):
Sharing a sentence is not in itself a finding about the gene and the disease.
atrial fibrillation (1 paper, 2018). A disorder characterized by an electrocardiographic finding of a supraventricular arrhythmia characterized by the replacement of consistent P waves by rapid oscillations or fibrillatory waves that vary in size, shape and timing and are accompanied by an irregular ventricular response. "Elevated levels of CXCL8, CCL11, CCL2, CXCL10, IL-1β, IL-6, TNF-α, IFN-γ, IL-17, IL-1Ra, IL-4, IL-9, FGF-basic, PDGF, G-CSF, and GM-CSF were observed in the Atrial fibrillation patient, in contrast to uninfected controls." (PMID 29370812, 2018).
biliary atresia (1 paper, 2019). A rare, biliary tract disease characterized by progressive obliterative cholangiopathy of the intra- and extrahepatic bile ducts, occurring in the embryonic/ perinatal period, leading to severe and persistent neonatal jaundice and acholic stool. "CCL11 (Eotaxin) was selectively increased in biliary atresia patients, while IL-3, IL-6, CXCL8 (IL-8), IL-9, IL-16, MIF, CCL4 (MIP-1 β), and CXCL1 (GRO-α), were increased in both biliary atresia and acute liver failure." (PMID 30740106, 2019). "In children with biliary atresia, serum levels of CCL11 (Eotaxin), IL-16, and GRO-α (CXCL1), as well as numbers of B lymphocytes, were higher than in children with ALF or liver tumors." (PMID 30740106, 2019).
bladder cancer (1 paper, 2024). "Furthermore, we reveal the involvement of two circulating inflammatory factors in bladder cancer at the same screening criteria (p<0.01), respectively as the level of Eotaxin (CCL11, OR: 1.26, 95% CI 1.06-1.49, p=0.0075) and IL-20 (OR: 1.40, 95% CI 1.09-1.82, p=0.0097) which are all risk factors." (PMID 39450166, 2024).
brain glioma (1 paper, 2024). A malignant glioma that involves the brain. "Our findings revealed that the serum levels of IL-4, IFN-α, IFN-γ, IL-6, TNF-α, CCL4, P-cadherin, TRAIL, CCL11, and VEGF were significantly higher in cases of brain inflammation compared with brain gliomas." (PMID 39364412, 2024).
cardiac hypertrophy (1 paper, 2022). "Ccl11 was also shown to be involved in angiotensin II-induced cardiac hypertrophy through the downstream regulation of pro-hypertrophic genes such as ANP, BNP and BMHC." (PMID 35380160, 2022).
cervical cancer (1 paper, 2020). A primary or metastatic malignant neoplasm involving the cervix. "In cervical cancer cells, CCL11/eotaxin-1 expression is increased, although the effect of chronic hypoxia on the expression of this chemokine is only indirect." (PMID 32781743, 2020).
corneal diseases (1 paper, 2022). "Furthermore, the severity of corneal diseases in AKC reportedly correlates with the concentration of eosinophils and eotaxin-1 (CCL11) in the tear fluid; therefore, CCL11 is thought to be an important chemokine that allows eosinophils to migrate to the cornea." (PMID 35326502, 2022).
coronary artery disease (1 paper, 2025). "A significant association between the A allele in the CCL11 67 G/A single-nucleotide polymorphism and a lower survival rate in patients with coronary artery disease was found in a Central European (Czech) population." (PMID 40149440, 2025).
coronary artery stenosis (1 paper, 2022). "CCL11 (eotaxin) plasma levels have been found to positively correlate to the score of coronary artery stenosis." (PMID 36189218, 2022).
coronary atherosclerosis (1 paper, 2024). Atherosclerosis of the coronary vasculature. "Additionally, the association of plasma CCL11 levels with the presence and extent of coronary atherosclerosis was examined in another study." (PMID 39465855, 2024).
Cryptococcal meningitis (1 paper, 2025). Meningeal inflammation produced by cryptococcus neoformans, an encapsulated yeast that tends to infect individuals with acquired immunodeficiency syndrome and other immunocompromised states. "Other variables including peripheral white blood cells, PD-L1, CXCL10, CCL11, IFN-γ, IL-2 and IL-10 did not independently predict the levels of CSF leukocytes count with cryptococcal meningitis." (PMID 39928682, 2025).
diabetic nephropathy (1 paper, 2024). "Although current reports on their associations with low-grade inflammation in patients with PD are lacking, it has been found that serum CCL11 levels are higher in CKD patients, potentially promoting interstitial inflammation in diabetic nephropathy and correlating with eGFR decline." (PMID 39444816, 2024).
diabetic neuropathy (1 paper, 2024). A chronic, pathological complication associated with diabetes mellitus, where nerve damages are incurred due to diabetic microvascular injury involving small blood vessels that supply these nerves, resulting in peripheral and/or autonomic nerve dysfunction. "Available data suggest that CCL11 may be important in later phases, rather than in the beginning, of diabetic neuropathy." (PMID 39457105, 2024).
diabetic retinopathy (1 paper, 2024). "There are a few studies that have measured CCL11/eotaxin-1 in eyes using vitreous fluid, but they focused on diabetic retinopathy and reported higher levels in patients with T2DM and retinopathy." (PMID 39201047, 2024). "Noticeably, despite the absence of diabetic retinopathy, IL-5, G-CSF, and CCL11/eotaxin-1 concentrations demonstrated a significant inverse correlation with MCV and MMT." (PMID 39201047, 2024).
endocrine cancers (1 paper, 2025). "Notably, endocrine cancers displayed the highest frequency of positive correlations with pro-inflammatory chemokine genes, particularly with CCL8, CCL11, CXCL1, CXCL5, and CXCL6, thus indicating a distinct regulatory pattern in this cancer subtype." (PMID 40806276, 2025).
esophageal cancer (1 paper, 2017). A primary or metastatic malignant neoplasm involving the esophagus. "In this study two chemokines (CCL11 and CXCL10) in the posttherapeutic tumor tissue were associated with prognosis in patients with esophageal cancer." (PMID 28537901, 2017). "Two chemokines (CCL11 and CXCL10) in posttherapeutic tumor tissue were associated with prognosis in patients with esophageal cancer, lower levels indicating a better prognosis." (PMID 28537901, 2017). "Little is known about CCL11 expression in esophageal cancer." (PMID 28537901, 2017).
food allergy (1 paper, 2012). Gastrointestinal disturbances, skin eruptions, or shock due to allergic reactions to allergens in food. "The reduction of CCL11 and CCL17 expression was also observed only in the ileum further providing support to this site being an “active” site of inflammation in a gastrointestinal food allergy immune response as well as a site of action of L. lactis NCC 2287." (PMID 21961022, 2012).
gout (1 paper, 2020). A condition characterized by painful swelling of the joints, which is caused by deposition of urate crystals. "Compared with WT mice, St2-/- mice showed significantly reduced expression of IL-1β, IL-6, IL-13, CCL11, G-CSF, CXCL1, CCL2 and CCL3 proteins in ankle tissues, suggesting St2-/- mice showed generally attenuated inflammatory response during gout." (PMID 33204337, 2020).
H1N1 influenza (1 paper, 2023). "The authors suggest a pivotal role of C-C motif chemokine 11 (CCL11), a chemokine associated with normal brain aging, in microglial dysfunction, similar to cognitive impairment syndrome due to H1N1 influenza and antineoplastic chemotherapy." (PMID 37239263, 2023).
Hashimoto thyroiditis (1 paper, 2023). An autoimmune disorder caused by the production of autoantibodies against thyroid tissue. "The genotype frequency of CCL11(rs3744508)AA(OR = 11.3) was higher in Hashimoto's thyroiditis (HT) patients, whereas that of CXCL8(rs2227306)CC(OR = 0.4) was lower in HT patients." (PMID 37730733, 2023).
HCMV infection (1 paper, 2020). "In particular, HCMV infection led mainly to the over-expression of CCL2, CCL3, CCL11, CXCR4, IL-1β, IL13, MMP1, MMP3, MMP9 and MMP13, SERPINA1, TNFα, and BMP7, and the gradual and constant downregulation of IL13RA2 (up to almost 800-fold at 14 days p.i.)." (PMID 32899126, 2020).
HIV-1 infection (1 paper, 2018). The type species of lentivirus and the etiologic agent of acquired immunodeficiency syndrome (AIDS). "Moreover, CCL11 has also previously been associated with more rapid CD4 loss below 350 cells/μl during acute HIV-1 infection." (PMID 29967620, 2018). "In previous studies, plasma levels of CCL11 have been related to a worse virological outcome during primary HIV-1 infection and post analytical treatment interruption." (PMID 29967620, 2018).
hookworm infection (1 paper, 2022). "This study discovered that a rise in intensity of hookworm infection (EPG) causes a corresponding increase in eosinophil count whereas the CCL11 level decreases." (PMID 35662977, 2022). "Specifically, we utilized a combination of plasma ECP, circulating eosinophil, CCL11, and IgE to identify and characterize immune responses in hookworm infection." (PMID 35662977, 2022). "Against this background, the current study assessed products of eosinophil‐mediated immune responses (CCL11, ECP, and IgE) as potential diagnostic markers for hookworm infection." (PMID 35662977, 2022). "ECP is the best predictive eosinophil‐mediated immune response marker for hookworm infection, while CCL11 and eosinophil count better predict hookworm intensity." (PMID 35662977, 2022). "ECP best predicts eosinophil‐mediated immune response for detecting hookworm infection, while CCL11 and eosinophil count better predict the intensity of hookworm." (PMID 35662977, 2022). "This activity of host immune response may account for the high levels of CCL11 in individuals with hookworm infection observed in this study." (PMID 35662977, 2022). "We investigated eosinophil‐mediated immune response as markers (CCL11, eosinophil cationic protein [ECP], and IgE) for detecting hookworm infection." (PMID 35662977, 2022). "However, eosinophil count (AUC = 0.59, p = 0.308), CCL11 (AUC = 0.69, p = 0.06), and IgE (AUC = 0.55, p = 0.408) count not significantly detect hookworm infection." (PMID 35662977, 2022).
hypereosinophilic syndrome (1 paper, 2018). Hypereosinophilic syndrome (HES) constitutes a rare and heterogeneous group of disorders, defined as persistent and marked blood eosinophilia and/or tissue eosinophilia associated with a wide range of clinical manifestations reflecting eosinophil-induced tissue/organ damage. "For example, eosinophils stimulated with CCL11/eotaxin-1 or tumor necrosis factor alpha (TNF-α) show increased numbers of cytoplasmic EoSVs as well as do naturally activated eosinophils from patients with hypereosinophilic syndrome when compared to normal donors." (PMID 30619361, 2018).
immunotoxicity (1 paper, 2018). "Results from the sparse PLS models selecting both exposures and proteins suggest a swimming-induced immunotoxicity through decreased level of IL-8, VEGF, CCL22, CCL11, CRP and CXCL10, and increased levels of IL-1ra, which antagonises the proinflammatory IL-1." (PMID 29563153, 2018).
Intellectual disability (1 paper, 2020). "An increased IL-8 level was correlated with the presence of intellectual disability, whereas interleukin-12, p70 (IL-12p70), and eotaxin-1 (CCL11) and granulocyte chemotactic protein 2 (GCP2) were associated specifically with the absence of intellectual disability." (PMID 32992922, 2020).
keloid (1 paper, 2020). An irregularly shaped, elevated mark on the skin caused by deposits of excessive amounts of collagen during wound healing. "Our results associate keloid tissues with an inflammatory milieu representing multiple T-helper pathways, including the Th2 (e.g. IL-4R, CCL11, TSLP, TNFSF4/OX40L, TNFRSF4/OX40), Th1 (e.g. IFNγ, CXCL10/11), Th17/Th22 (e.g. PI3, CCL20, S100As) axes, as well as the JAK/STAT signaling molecule JAK3." (PMID 33329590, 2020). "The up-regulation of T-cell related genes in non-lesional skin compared to normal skin (e.g. CCL11, CCR5) highlight that the seemingly normal skin of keloid patients is in fact abnormal and predisposed to formation of keloids." (PMID 33329590, 2020).
mental disorder (1 paper, 2016). A disease that has its basis in the disruption of mental process. "Regarding the diagnosis of comorbid mental disorders, we observed significant effects on CCL11 concentrations." (PMID 28149283, 2016). "Only CCL11 concentrations were found to be altered in AUD patients diagnosed with mental disorders (p < 0.01) with a strong main effect of sex." (PMID 28149283, 2016).
microcephaly (1 paper, 2021). A congenital or acquired developmental disorder in which the circumference of the head is smaller than normal for the person's age and sex. "When the groups of neonates with microcephaly and controls were compared, we identified the top discriminant scores for IL-1β, IL-3, EOTAXIN (CCL11) and IL-12p70." (PMID 33875756, 2021). "In the canonical coefficient analysis between controls and those exposed to ZIKV without microcephaly, we found that IL-1β, IL-3, IL-4, IL-7 and EOTAXIN (CCL11) were the top CSF markers in our model." (PMID 33875756, 2021).
mycosis fungoides (1 paper, 2021). Classical mycosis fungoides is the most common type of mycosis fungoides (MF), a form of cutaneous T-cell lymphoma, and is characterized by slow progression from patches to more infiltrated plaques and eventually to tumors. "In patients with CTCL [either mycosis fungoides (MF) or Sézary syndrome (SS)], serum concentrations of CCL11 and CCL17 were increased and correlated with disease activity." (PMID 34503058, 2021).
myocardial disease (1 paper, 2020). "The role of eotaxin-1/CCL11 in myocardial disease is largely unknown." (PMID 32147601, 2020).
myocarditis (1 paper, 2025). Myocarditis is a condition that is characterized by inflammation of the heart muscle (myocardium). "A previous study showed that CCL11 was also involved in the recruitment of eosinophils which have a pathogenic effect in the development of myocarditis, while inhibiting this pathway has been demonstrated to have a protective effect against cardiac damage in mice models." (PMID 40684041, 2025).
neuronal tumor (1 paper, 2020). Neuronal brain tumors are an uncommon group of central nervous system tumors that arise from cells with neuronal differentiation. "Interestingly, the effect of VX765 treatment differed in neuronal tumors where elevated levels of CCL11 and CCL26 were found in SH-SY5Y compared to untreated controls, and no changes in cytokine levels were detected in VX765 treated U138MG cells compared to controls." (PMID 33613529, 2020).
ocular toxoplasmosis (1 paper, 2023). Ocular toxoplasmosis is an infection in the eye caused by the parasite, Toxoplasm a gondii. "In another study, patients with ocular toxoplasmosis displayed high levels of IFN-induced chemokines CXCL9 and CXCL10 and circulating chemokines CCL25, CCL11, CXCL12, CXCL13, and CCL2." (PMID 36755348, 2023).
osteosarcoma (1 paper, 2024). A usually aggressive malignant bone-forming mesenchymal neoplasm, predominantly affecting adolescents and young adults. "At one month following tumor-clearing CAR T cell therapy, the aggressive osteosarcoma model exhibited persistently elevated serum levels of CCL11, CCL2 and BAFF compared to tumor-bearing, mock T cell-treated control mice." (PMID 38798554, 2024). "Prominently, we observed persistently elevated levels of eotaxin/CCL11, CCL2, CCL7, CXCL1, CXCL10 and BAFF in the DIPG, ALL, and aggressive osteosarcoma models, the same three models that also exhibit cognitive deficits." (PMID 38798554, 2024).
pancreatic ductal adenocarcinoma (1 paper, 2018). An infiltrating adenocarcinoma that arises from the epithelial cells of the pancreas. "Recent study hypothesized that eotaxin-1/CCL11 recruits MDSCs in pancreatic ductal adenocarcinoma but in the end the fact is proved to be contrary to this hypothesis." (PMID 29499727, 2018).
pericarditis (1 paper, 2022). An inflammatory process affecting the pericardium. "Exogenous IL-33 expanded murine pericardial ILC2s, driving cardiac fibroblasts to secrete CCL11/eotaxin-1 and recruit eosinophils, initiating pericarditis." (PMID 35359972, 2022).
periodontal disease (1 paper, 2022). "Production of CC chemokine ligand 11 (CCL11) in human gingival fibroblasts (HGFs) is associated with the migration of Th2 lymphocytes in the pathogenesis of the periodontal disease." (PMID 35706460, 2022).
peripheral vascular disease (1 paper, 2024). Any disorder affecting blood flow through the veins or arteries outside of the heart. "Based on these findings, supplements of chemokines CCL11 may be a new therapeutic strategy for inducing neovascularization and improving perfusion recovery, thereby preventing the occurrence of adverse events such as disability and death in peripheral vascular diseases." (PMID 38906863, 2024).
Pf (1 paper, 2019). "Pairwise mean differences of the cytokine levels between all the infected groups showed that individuals infected with only Na had significantly higher CCL11 and IL-5 levels compared to those with either Pf only or concurrent Na/Pf infections." (PMID 33604551, 2019).
pollen allergy (1 paper, 2025). "This is supported by the fact that in this group, pollen allergy, with sensitivities to grass allergens (85%) and tree allergens (birch 66%, alder 68%, hazel 64%), predominated, in contrast to the subgroup with EoE (33%) and the subgroup with negative CCL-11 staining (13%)." (PMID 40284218, 2025).
primary immunodeficiency (1 paper, 2024). "KEGG analysis associated CCL11 expression with Cytokine−cytokine receptor interaction, viral protein interaction with cytokine and cytokine receptor, and primary immunodeficiency." (PMID 38305920, 2024).
renal clear cell carcinoma (1 paper, 2020). "Using a FDR of q < 0.05, analyzes revealed that high IL6 expression was associated with higher odds of death for renal clear cell carcinoma (n = 530, HR = 2.49, 95% CI 1.78‐3.49, P < .001), as was high CCL11 (HR = 1.91, 95% CI 1.41‐2.60, P < .001)." (PMID 32383556, 2020). "Conversely, elevated CCL11 was associated with improved odds of survival in HNSCC and OTSCC subgroup but increased odds of death for renal clear cell carcinoma." (PMID 32383556, 2020).
Schistosomiasis japonica (1 paper, 2020). Schistosomiasis caused by Schistosoma japonicum. "Our data showed that after S. japonicum infection, a large number of eosinophils around granulomas in the livers, spleens, and large intestines of mice with advanced schistosomiasis japonica, as expected, the levels of CCL11 and CCL24 were increased in the liver, spleen, or large intestine." (PMID 32231658, 2020).
Sciatica (1 paper, 2024). Pain in the lower back and hip radiating in the distribution of the sciatic nerve. "For instance, several key chemokines including CCL2, CCL11, CXCL5, CXCL6, and IL-16 were positively associated with sciatica." (PMID 39015317, 2024).
spinal injury (1 paper, 2021). A injury that involves the vertebral column. "The levels of cytokines CXCL5, CCL11, CXCL11, IL10, TNFα, and MIF were different between patients with baseline American Spinal Injury Association Impairment Scale (AIS) grades of A or B, whilst IL2 (>2 fold) and MIP-3a (>6 fold) were significantly expressed in the cervical and thoracic regions." (PMID 33806460, 2021).
thymoma (1 paper, 2024). A neoplasm arising from the epithelial cells of the thymus. "Patients with hyperplasia and thymoma differed in several proteins, including IL-18R1, TRAIL, CCL23, CX3CL1, CD8A, IL-8, TNF-β, and CCL11." (PMID 39165841, 2024).
urticaria (1 paper, 2016). A vascular reaction of the skin characterized by erythema and wheal formation due to localized increase of vascular permeability. "CCL11, CCL17, CCL26, and CCL27 are implicated in the pathogenesis of urticaria." (PMID 27057079, 2016). "In our study, serum levels of CCL11, CCL17, CCL26, and CCL27 increased significantly in both AU and CSU patients, indicating that elevated CCL11, CCL17, CCL26, and CCL27 are involved in the pathogenesis of urticaria." (PMID 27057079, 2016).